MRPL13 (mitochondrial ribosomal protein L13)
Synonyms: L13mt; L13; RPL13; RPML13; L13A; uL13m
Tractability: Small molecule: a structure with a bound ligand is known. PROTAC: ubiquitination databases record sites on it; its protein half-life has been measured.
Gene: Protein-coding gene on chromosome 8 (120,380,761 to 120,445,402, reverse strand). Ensembl gene ENSG00000172172.
Subcellular location: Mitochondrion
Pathways (Reactome):
Metabolism of proteins: Mitochondrial ribosome-associated quality control; Mitochondrial translation elongation; Mitochondrial translation initiation; Mitochondrial translation termination
Gene Ontology:
Molecular function: protein binding; RNA binding; structural constituent of ribosome
Biological process: mitochondrial translation; negative regulation of translation; translation
Cellular component: mitochondrial large ribosomal subunit; mitochondrial ribosome; mitochondrion; mitochondrial inner membrane; ribosome
Genetic constraint (gnomAD): Loss-of-function variants: 18 observed, 13.65 expected, observed/expected ratio (o/e) 1.32, 90% interval 0.91 to 1.84. The upper end of that interval is the gene's LOEUF score, 1.84, which puts it in group 6 of 6, group 1 being the genes least tolerant of losing a copy. Missense variants: 115 observed, 106.62 expected, observed/expected ratio (o/e) 1.08, 90% interval 0.93 to 1.26. Synonymous variants: 39 observed, 33.57 expected, observed/expected ratio (o/e) 1.16, 90% interval 0.9 to 1.52.
Homologues: Orthologues: chimpanzee MRPL13 (99% identical), macaque MRPL13 (99% identical), pig MRPL13 (92% identical), guinea pig MRPL13 (89% identical), mouse Mrpl13 (89% identical), rabbit MRPL13 (88% identical), dog MRPL13 (82% identical), rat Mrpl13 (81% identical), zebrafish mrpl13 (78% identical), tropical clawed frog mrpl13 (72% identical), Drosophila melanogaster mRpL13 (47% identical), Caenorhabditis elegans mrpl-13 (39% identical). Paralogues in human: RPL13A (27% identical).
Diseases named in the same sentence as MRPL13 in open-access papers:
MRPL13 is named in the same sentence as 27 diseases in open-access papers, as found by Europe PMC text mining. Sharing a sentence is not in itself a finding about the gene and the disease. The quoted sentences say what the papers report.
breast carcinoma (18 papers, 2018 to 2025). "Taken together, MRPL13 is a diagnostic and prognostic biomarker for several types of cancer, including lung cancer, breast cancer, and gastric cancer." (PMID 39859078, 2025). "High MRPL13 expression was associated with adverse clinicopathological variables and unfavorable clinical outcomes in breast cancer patients." (PMID 39859078, 2025). "CIBERSORT analysis shows that higher MRPL13 expression in breast cancer is significantly associated with reduced NK cell infiltration." (PMID 40371222, 2025). "High MRPL13 expression is associated with a worse prognosis in several types of cancer, including lung cancer, breast cancer, and gastric cancer." (PMID 39859078, 2025). "Analysis of microarray data from 3,951 breast cancer tumours also found that recurrence and distant metastasis were associated with increased MRPL13." (PMID 39354291, 2024). "Using an informatics-based approach, one study observed that MRPL13 expression was associated with breast cancer tumour recurrence and hormone resistance across several Gene Expression Omnibus (GEO) datasets (n = 3,455)." (PMID 39354291, 2024). "For instance, higher MRPL13 expression was significantly associated with worse survival, and was identified as a novel prognostic biomarker in breast cancer." (PMID 36769082, 2023). "Here, we had identified that MRPL12 and MRPL13 also could be regarded as potential risk factors for breast cancer." (PMID 34322380, 2021). "The expression levels of MRPL13 in metastatic breast cancer tissues were obviously higher than those in primary breast cancer tissues." (PMID 39859078, 2025). "MRPL13 is overexpressed in breast cancer, lung cancer, and gastric cancer, serving as a potential predictive biomarker, with its high expression correlated with poor patient prognosis." (PMID 40841355, 2025). "In breast cancer, MRPL13 promotes cell proliferation, migration, and epithelial-mesenchymal transition via the PI3K/AKT/mTOR pathway, contributing to metastasis and recurrence." (PMID 40841355, 2025). "Recent studies have revealed that MRPL13 is abnormally expressed in several malignancies, such as breast cancer, gastric cancer, liver cancer, and lung cancer, and plays a significant role in driving malignant progression." (PMID 40841355, 2025). "MRPL13 is dysregulated in many types of cancer, including breast cancer, colorectal cancer (CRC), gastric cancer, and lung cancer." (PMID 39859078, 2025). "Analyses of breast cancer TCGA data showed high MRPL13 expression correlated with poor prognosis, as well as advanced tumour stage, increased immune infiltration and metastasis." (PMID 39354291, 2024). "In breast cancer, MRPL13 is involved in cell proliferation and EMT processes and is associated with poor prognosis in patients." (PMID 37946181, 2023). "In breast cancer, MRPL13 is involved in cell proliferation and EMT process, and is associated with poor prognosis of patients." (PMID 37946181, 2023). "Studies have shown that inhibiting MRPL13 can slow down the proliferation of breast cancer cells and EMT process, while reducing the resistance of non-small cell lung cancer cells to anthracyclines chemotherapy drugs." (PMID 37946181, 2023). "In vitro, MRPL13 silencing significantly inhibits the proliferation of breast cancer cells and changes the expression pattern of EMT-related genes by eliminating the positive contribution of AKT and mTOR phosphorylation." (PMID 37827692, 2023). "As a poor prognostic factor in breast cancer, MRPL13 expression is significantly higher in cancer tissues than in normal tissues." (PMID 35719986, 2022). "For example, MAL2 and MRPL13 can inhibit tumor antigen presentation to drive breast cancer immune escape, and upregulation of two genes in breast cancer has been demonstrated to drive malignant progression of cancer." (PMID 36267313, 2022).
breast carcinoma (continued). "Oval all, we identified three RBP-coding genes (MRPL12, MRPL13 and POP1) that functioned as risk factors and independent prognostic factors for breast cancer." (PMID 34322380, 2021). "The co-expression network revealed that ELAVL2, VIM, MRPS12, HSPE1, EZH2, HIST1H4B, and MRPL13 played a vital role in the progression of breast cancer, and we further selected important modules of target genes through MCODE." (PMID 30881302, 2019). "Similarly, knocking down MRPL12 and MRPL13 in vitro significantly inhibits breast cancer cell activity and migration." (PMID 40371222, 2025). "Similarly, MRPL13 promotes the growth and spread of breast cancer by influencing cellular metabolism and energy demands, and its high expression is significantly correlated with clinical pathological factors and considered a poor prognostic indicator." (PMID 40371222, 2025). "Therefore, MRPL13 not only serves as a biomarker for predicting treatment response in breast cancer patients but also provides a new target for evaluating and optimizing immunotherapy." (PMID 40371222, 2025). "Furthermore, in vitro studies have found that downregulation of MRPL13 inhibited migration and decreased cell viability in bone and lung metastasised breast cancer cell lines." (PMID 39354291, 2024). "Additionally, another study identified high MRPL13 expression as a poor prognostic factor in breast cancer, proposing its use both as a prognostic marker and a potential therapeutic target." (PMID 38310106, 2024). "This suggests that TP53AIP1 and ME3 may function as tumor suppressors, and MRPL13 might act as an oncogene in breast cancer." (PMID 38310106, 2024). "MRPL13 was first identified as a potential prognostic biomarker in breast cancer." (PMID 39354291, 2024). "In this context, some strategies that targeting the MRPL12, MRPL13 or even the mitoribosome might be practicable in curing breast cancer." (PMID 34322380, 2021). "In conclusion, ABCA3, CCL22, FOXJ1, MAP2K6, and IL1RN may serve as good prognostic factors, while KCNIP3 and MRPL13 may be poor prognostic biomarkers to predict the recurrence and prognosis of breast cancer." (PMID 32977823, 2020). "ABCA3, CCL22, FOXJ1, IL1RN, and MAP2K6 may serve as good prognostic factors, while KCNIP3 and MRPL13 may be poor prognostic factors for the prognosis of breast cancer." (PMID 32977823, 2020). "However, MRPL13 and KCNIP3 were predicted to be risk factors associated with poor prognostic outcome in breast cancer." (PMID 32977823, 2020). "MRPL13 promotes cell proliferation, migration, and epithelial–mesenchymal transition (EMT) in breast cancer by activating the PI3K/AKT/mTOR signaling pathway." (PMID 39770478, 2024). "Studies have shown that inhibiting MRPL13 can slow down the proliferation and EMT process of breast cancer cells." (PMID 37946181, 2023). "In breast cancer, a three-gene prognostic model based on MRPL12, MRPL13, and POP1 has significant predictive value for survival." (PMID 35719986, 2022). "In addition, the expression pattern of MRPL12, MRPL13 or POP1 were significantly associated with tumor stage, suggesting that these three RBP-coding genes could be regarded as potential biomarkers for breast cancer prognosis." (PMID 34322380, 2021). "Although MRPL12, MRPL13 or POP1 were over-expressed in tumor tissues, there were also some slight differences in expression pattern between each subtype of breast cancer, wherein TNBC cases tolerated the highest expression of these three RBPs." (PMID 34322380, 2021). "All these results suggested that MRPL12, MRPL13 and POP1 should be designed as biomarkers and potential intervening targets for breast cancer." (PMID 34322380, 2021). "Furthermore, down-regulating the expression of endogenous MRPL12, MRPL13 or POP1 in breast cancer cells, resulted in dramatically suppression of cellular viability and migration, suggesting that these three RBP-coding genes might act as oncogenes in accelerating the progress of breast cancer." (PMID 34322380, 2021).
breast carcinoma (continued). "Similarly, the bioinformatics analysis found that MRPL13 may have a prognostic value for breast cancer, the survival rate of breast cancer patients with a high expression of MRPL13 was relatively low, which could be used as a potential prognostic marker for breast cancer." (PMID 33238645, 2020). "Functional studies have shown that MRPL13 promotes proliferation and migration as well as epithelial-mesenchymal transition (EMT) process by triggering activation of the PI3K/AKT/mTOR signaling pathway in breast cancer cells." (PMID 40371222, 2025). "Moreover, analogous to MRPL12 and MRPL13, our results also revealed that POP1 functioned as an oncogene in breast cancer." (PMID 34322380, 2021). "Besides, some compounds (such as the Acetaminophen, Urethane and Tunicamycin) were predicted for curing breast cancer via targeting MRPL12, MRPL13 and POP1 simultaneously." (PMID 34322380, 2021). "In alignment with our results, we speculated that MRPL13 and KCNIP3 may be served as poor prognostic biomarkers, and their downregulation may have a better prognosis of breast cancer." (PMID 32977823, 2020). "The survival analysis suggested that DCAF13, EZR, MRPL13, APOBEC3C, and EIF4E3 might have a prognostic value for breast cancer." (PMID 30881302, 2019). "Another study found that MRPL13 knockdown inhibits invasion in both non-invasive (MCF-7, T47D) and invasive (MDA-MB-231) breast cancer cells, partly through diminished EMT processes, which suggests that MRPL13 expression may contribute to the acquisition of metastatic traits in breast cancer." (PMID 39354291, 2024). "These authors concluded that MRPL12, MRPL13, and POP1 might act as oncogenes in maintaining cellular viability and stimulating the metastasis of breast cancer cells, involving the possibility of their being designed as biomarkers and/or therapeutic targets for breast cancer." (PMID 37298568, 2023). "Moreover, the downregulation of endogenous MRPL12, MRPL13, or POP1 expression could significantly inhibit the viability and migration of breast cancer cells in vitro." (PMID 35719986, 2022). "MRPL12, MRPL13 and POP1 might act as oncogenes in maintaining cellular viability and accelerating metastasis of breast cancer cells, implying the possibility of which to be designed as biomarkers and/or therapeutic targets for breast cancer." (PMID 34322380, 2021). "All these results indicated that MRPL12, MRPL13 and POP1 not only could be designed as prognostic factors for predicting survival probability of patients with breast cancer, but also could be used as potential targets for clinical intervention of breast cancer." (PMID 34322380, 2021). "Furthermore, we performed some preliminary experiments and provided concrete evidence that MRPL12, MRPL13 and POP1 might be oncogenes in maintaining cellular viability as well as accelerating metastasis of the breast cancer cells." (PMID 34322380, 2021). "All these results confirmed that MRPL12, MRPL13 and POP1 acted as oncogenes in breast cancer cells, therefore, they might be regarded as prognostic indicators in breast cancer, but also could be designed as therapeutic targets of breast cancer." (PMID 34322380, 2021). "Furthermore, experimental validations showed that down-regulating the expression of endogenous MRPL12, MRPL13 or POP1 could dramatically suppress the cellular viability and migration of breast cancer cells in vitro." (PMID 34322380, 2021). "The role of MRPL13 in breast cancer has not been reported to our knowledge." (PMID 32977823, 2020). "Notably, by reviewing the Comparative Toxicogenomics Database (CTD), we excavated three available compounds (Acetaminophen, Urethane and Tunicamycin), which could inhibit the MRPL12, MRPL13 and POP1 simultaneously, implying their anti-neoplastic effects on breast cancer." (PMID 34322380, 2021).
hepatoma (10 papers, 2019 to 2025). "In a study, reduced MRPL13 expression in hepatocellular carcinoma was a key factor in the regulation of mitochondrial ribosome and subsequent OXPHOS deficiency, which regulates the aggressive activity of liver cancer cells." (PMID 30881302, 2019). "However, MRPL13 suppression is a cause of mitochondrial defects in HCC and promotes the invasiveness of mitochondria-defective hepatoma cells." (PMID 34772924, 2021). "Previous studies have demonstrated that suppressing MRPL13 expression leads to mitochondrial ribosome defects, weakening OXPHOS activity and affecting the invasiveness of hepatocellular carcinoma cells." (PMID 40841355, 2025). "Inhibition of MRPL13 has been shown to precipitate OXPHOS dysfunction and enhance the invasiveness of hepatoma cells." (PMID 39913623, 2025). "MRPL44 expression was identified as a predictor of lymph node metastasis in papillary thyroid carcinoma, and MRPL13 inhibition was shown to be a key upstream regulator of OXPHOS dysfunction and hepatoma cell invasiveness." (PMID 36233293, 2022). "MRPL44 expression was identified as a predictor of lymph node metastasis in papillary thyroid carcinoma, and MRPL13 suppression was shown to be a key upstream regulator of OXPHOS dysfunction and hepatoma cell invasiveness." (PMID 34772924, 2021). "Interestingly, downregulation of MRPL13 restrained the proliferation and migration of BC35, whereas it enhanced the invasiveness of hepatoma via the reactive oxygen species (ROS)-Claudin-1 pathway." (PMID 35739158, 2022).
lung carcinoma (7 papers, 2020 to 2025). "Experimental findings also indicate that the expression of MRPL13 is significantly higher in lung cancer tissues than in normal tissues." (PMID 40371222, 2025). "We chose A549 and NCI-H1975 lung cancer cell lines for further experiments based on their expression of MRPL13 and experimental feasibility." (PMID 37827692, 2023). "In addition to MRPL4, MRPL13 has been widely studied across breast and lung cancer and holds promise as a putative metastatic prognostic target." (PMID 39354291, 2024). "Gene set enrichment analysis (GSEA) results suggest that MRPL13 may participate in the development and progression of lung cancer by modulating key signaling pathways such as MYC targets, PI3K/AKT/mTOR signaling, oxidative phosphorylation, and the G2/M checkpoint." (PMID 40371222, 2025). "Therefore, repurposing them to target MRPs, such as MRPL13 and MRPL9 in aggressive lung cancer is a promising area of future research." (PMID 39354291, 2024).
liver cancer (5 papers, 2019 to 2023). An epithelial or non-epithelial malignant neoplasm that arises from the liver. "The MRPS have also been reported to be active in HCC, and it has been shown that high levels of MRPL13 promote the invasion of liver cancer cells." (PMID 38093387, 2023). "MRPL13 expression was significantly increased in multiple human cancers, such as bladder cancer, colon cancer, liver cancer, and prostate cancer." (PMID 34868337, 2021). "It has been shown that the high levels of MRPL13 promote invasion of liver cancer cells." (PMID 38093387, 2023).